RNU6-373P (RNA, U6 small nuclear 373, pseudogene)
Gene: Small nuclear RNA gene on chromosome 5 (119,007,571 to 119,007,668, forward strand). Ensembl gene ENSG00000223179.
Homologues: Orthologues: chimpanzee U6 (98% identical), macaque U6 (92% identical). Paralogues in human: RNU6-944P (83% identical), RNU6-1243P (82% identical), RNU6-140P (82% identical), RNU6-43P (82% identical), RNU6-595P (82% identical), RNU6-698P (82% identical), RNU6-892P (82% identical), RNU6-98P (82% identical), RNU6-1019P (81% identical), RNU6-1037P (81% identical), RNU6-1050P (81% identical), RNU6-1122P (81% identical), and 1286 more.